ROCK1 (Rho associated coiled-coil containing protein kinase 1)
Diseases named in the same sentence as ROCK1 in open-access papers (continued):
Sharing a sentence is not in itself a finding about the gene and the disease.
endothelial dysfunction (6 papers, 2016 to 2023). In vascular diseases, endothelial dysfunction is a systemic pathological state of the endothelium (the inner lining of blood vessels) and can be broadly defined as an imbalance between vasodilating and vasoconstricting substances produced by (or acting on) the endothelium. "For instance, salvianolic acid B protects against endothelial dysfunction by inhibiting Rho-associated protein kinase 1 (ROCK1)-mediated mitophagy and apoptosis." (PMID 36860298, 2023). "Caspase 3 has been reported to cleave the Rho-associated protein kinase ROCK1 into its active form, which is involved in endothelial dysfunction." (PMID 36674690, 2023). "Our results demonstrated that the S1PR2 antagonist (JTE-013) almost completely blocked endothelial dysfunction and associated fission and dysfunction of mitochondria under HG conditions along with down-regulated HG-promoted expression of RhoA/ROCK1." (PMID 30999892, 2019). "The RhoA/mDia-1 (mammalian diaphanous homolog-1)/profiling-1 or RhoA/ROCK1 (Rho-associated coiled-coil-containing protein kinase 1) pathways have been shown to be involved in the pathology of DR via triggering microvascular endothelial dysfunction." (PMID 26881246, 2016). "Generally, RhoA/ROCK1 pathway activation leads to the progression of cardiovascular diseases through inflammation, endothelial dysfunctions, VSMCs contraction, proliferation and migration." (PMID 37278388, 2023). "For instance, Sal B alleviates oxidized low-density lipoprotein- and high glucose (HG)-induced endothelial dysfunction through weakening ROCK1-mediated mitophagy and apoptosis." (PMID 35068334, 2022). "Additionally, the permeability, apoptosis, and migration of cells were determined to evaluate the effects of S1PR2 and ROCK1 inhibition on high glucose-induced endothelial dysfunction." (PMID 30999892, 2019). "Moreover, it may protect against oxLDL- and HG-induced endothelial dysfunction through downregulation of ROCK1-modulated mitophagy and apoptosis." (PMID 35068334, 2022).
Hepatic steatosis (6 papers, 2019 to 2025). Steatosis is a term used to denote lipid accumulation within hepatocytes. "A similar finding was obtained in ob/ob (leptin deficient) and db/db (leptin receptor deficient) mice aged 10 weeks, as well as humans with fatty liver disease, in which the hepatic ROCK1 level was found to be increased compared with that in controls." (PMID 30919598, 2019).
pulmonary hypertension (6 papers, 2015 to 2025). Increased pressure within the pulmonary circulation due to lung or heart disorder. "Currently, studies on the relationship between pulmonary hypertension and ROCK1 and ROCK2 were limited to lung tissue level." (PMID 29921927, 2018). "However, the study of pulmonary hypertension in the plateau region is limited, and the detection of serum ROCK1 and ROCK2 in pulmonary hypertension patients is much more convenient." (PMID 29921927, 2018). "ROCK inhibitors, such as fasudil, are in clinical trial for pulmonary hypertension and our studies suggest a potential beneficial effect of ROCK1 inhibitor for patients on dasatinib who develop peripheral edema, pleural pulmonary edema, and pulmonary hypertension." (PMID 28316141, 2017). "Moreover, increased ROCK function was also found to be involved in pulmonary hypertension, and again transcription levels of ROCK1 were more markedly enhanced than transcription levels of ROCK2 in both rat and human." (PMID 26468005, 2015). "Fasudil, a dual ROCK1/2 inhibitor approved in Japan and China for cerebral vasospasm and pulmonary hypertension, is a promising agent for NASH treatment due to its observed safety, efficacy, and anti-fibrotic effect (IC50 = 0.18 μM [ROCK1] and 0.06 μM [ROCK2])." (PMID 38172941, 2024).
Cerebral ischemia (5 papers, 2019 to 2022). Restriction of arterial blood supply to the brain associated with insufficient oxygenation to support the metabolic requirements of the tissue. "Another study has shown that SNHG14 can assist in induction of inflammatory response by cerebral ischemia/reperfusion (I/R) injury via regulating miR-136-5p/ROCK1 axis." (PMID 36177350, 2022). "Most studies focus on the important roles of ROCK1 in pathogenesis of cardiac system ischemia disease, only few studied its function in cerebral ischemia." (PMID 30546117, 2019). "ROCK1/ROCK2 inhibitors rescued the efficacy of BBB damage in several CNS diseases, including experimental autoimmune encephalomyelitis, cerebral ischemia, and intracerebral hemorrhage." (PMID 33548010, 2021).
esophageal squamous cell carcinoma (5 papers, 2020 to 2026). Esophageal squamous cell carcinoma (ESCC) is a type of esophageal carcinoma (EC) that can affect any part of the esophagus, but is usually located in the upper or middle third. "For example, esophageal squamous cell carcinoma invasion and migration are attenuated by ROCK1 deletion in vitro." (PMID 32554853, 2020).
ischemic stroke (5 papers, 2016 to 2025). A stroke disorder caused by obstruction of blood flow to the brain, due to thrombotic (local blood clot formation) or embolic (due to a blood clot or other material traveling from another site) event. "Collectively, these findings validate the neuroprotective efficacy of Y-27632 through inhibition of the ROCK1/MLC/NMMHC IIA signaling axis in ischemic stroke." (PMID 41165828, 2025). "Coincidentally, a prior work has mentioned that ROCK1 cooperates with the NF-κB pathway to mediate ischemic stroke." (PMID 34399695, 2021). "Of note, SLx-2119, that has 100-fold more selectivity towards ROCK2 than ROCK1, has been suggested to be a potential drug for the treatment of ischemic stroke, autoimmune disease and psoriasis." (PMID 30884801, 2019). "The DOH and DA targeting of ROCK1/2 as revealed by our kinome screenings could therefore contribute to the ischemic stroke prophylactics and memory benefits that were reported for AGN." (PMID 39779619, 2025).
lymph node metastasis (5 papers, 2014 to 2020). "Since AHR, RhoA and ROCK1 were all associated with lymph node metastasis and clinical stage, and they correlated significantly with each other, we wondered if they had any relationships with overall survival time." (PMID 32546278, 2020). "In lymph node metastasis group, ROCK1 expression was found to be higher in 6 NSCLC tissues out of 10 NSCLC tissues." (PMID 31638991, 2019). "Rac1, Pak1 and Rock1 expression in the lymph node metastasis group (75, 71 and 66%) were significantly higher than in the group without metastasis (51, 43 and 41%)." (PMID 23298303, 2014). "The Rock1 expression rate in lymph node metastasis was 66 percent, which is significantly higher than in the group without metastasis (41%) (P < 0.05)." (PMID 23298303, 2014). "Greater expression of ROCK1 was associated with the absence of lymph node metastasis (p = 0.022) and a lower depth of invasion (p = 0.002)." (PMID 25380619, 2014). "Also, higher expression of ROCK1 was linked to greater survival, the absence of lymph node metastasis, and a lower depth of invasion." (PMID 25380619, 2014). "The expression level of miR-335-5p and ROCK1 in 60 paired NSCLC tissues were further classified to subgroups according to presence or absence of lymph node metastasis." (PMID 31638991, 2019). "The differential expression level of miR-335-5p and ROCK1 were determined by qRT-PCR and IHC analysis in human tissue samples with or without lymph node metastasis." (PMID 31638991, 2019). "Moreover, we performed IHC analysis to compare ROCK1 expression in 10 patients samples with or without lymph node metastasis seperately." (PMID 31638991, 2019). "Our data showed that aspects that are related to a good prognosis, such as the absence of lymph node metastasis, lower depth of invasion, and better survival, correlated with ROCK1 immunoexpression, suggesting that ROCK1 is a marker of good prognosis in vulvar cancer." (PMID 25380619, 2014).
metabolic syndrome (5 papers, 2020 to 2025). A cluster of metabolic risk factors for CARDIOVASCULAR DISEASES and TYPE 2 DIABETES MELLITUS. "Furthermore, the consistent upregulation of ROCK1 and TGF-β1 in our metabolic syndrome model and their modulation by cranberries reinforce their synergistic roles in fibrotic processes." (PMID 40954151, 2025). "Interestingly, therapeutic agents metformin and paeoniflorin target hepatic ROCK1/AMPK signaling to improve steatosis and dyslipidemia in DIO mice and palmitate treated HepG2 cells, respectively." (PMID 33633690, 2020).
myocardial infarction (5 papers, 2017 to 2022). Gross necrosis of the myocardium, as a result of interruption of the blood supply to the area, as in coronary thrombosis. "In the mouse model of myocardial infarction, Rock1−/− and Rock1+/− mice showed reduced cardiac fibrosis." (PMID 32178482, 2020). "Data from experimental animal models showed that complete or partial deletion of Rock1 or Rock2 protected mice from fibrosis during hypertensive cardiac remodelling and following myocardial infarction." (PMID 32178482, 2020). "The reducing rate of TFR in myocardial infarction area, RhoA activity, and ROCK1, ROCK2, and p-MLC protein expressions in UTR knockdown rats decreased markedly compared with that in WT rats." (PMID 29541143, 2018). "Myocardial infarction, ST-segment elevation, and the expression of UTR, ROCK1, ROCK2, and p-MLC protein in rat myocardium were determined at 90 min after reperfusion." (PMID 29541143, 2018).
myocardial ischemia (5 papers, 2020 to 2025). A disorder of cardiac function caused by insufficient blood flow to the muscle tissue of the heart. "Fasudil, a Rock1 inhibitor, was used to inhibit the expression of Rock1 in a variety of cardiovascular disease, such as diabetic cardiomyopathy and myocardial ischemia/reperfusion injury." (PMID 39755713, 2025). "It has been pointed out that Rock1 phosphorylates Drp1 to promote mitochondrial fission in response to myocardial ischemia/reperfusion injury." (PMID 39755713, 2025). "More importantly, available report suggested that oxycodone ameliorated myocardial ischemia-reperfusion injury in rats via RhoA/ROCK1 signaling." (PMID 35170371, 2022). "The miR-335/ROCK1 axis regulated multiple functions, including tumor progression, myocardial ischemia/reperfusion, and chondrogenesis." (PMID 32219065, 2020).
omphalocele (5 papers, 2012 to 2024). Omphalocele is an embryopathy classified in the group of abdominal celosomias and is characterized by a large hernia of the abdominal wall, centered on the umbilical cord, in which the protruding viscera are protected by a sac. "Rock1 constitutive knockout mice survive to birth, with the most prominent phenotypes being omphalocele and unfused eyelids." (PMID 35737725, 2022). "The majority of ROCK1–/– mice (> 90%) die soon after birth due to organs protruding through an omphalocele, such as the liver and gut through the peritoneal cavity." (PMID 35043239, 2022). "ROCK1 knockout (KO), ROCK2 KO, and ROCK1/2 double heterozygous mice has been reported to exhibit omphalocele phenotype due to disorganization of actin filament in the epithelial cells of umbilical ring." (PMID 29555972, 2018). "In addition, single knockout embryos of either ROCK1 or ROCK2, as well as ROCK1+/−ROCK2+/− embryos, show omphalocele and impaired eyelid opening at birth." (PMID 38604990, 2024). "ROCK1–/– mice in C57BL/6 genetic background were born at expected Mendelian ratios, but exhibited eyelids open at birth (EOB) and an omphalocele phenotype due to disorganization of actin filaments in the epithelial cells of the eyelids and in the umbilical ring." (PMID 35043239, 2022). "In contrast, the mice in FVB background exhibit a different embryonic phenotype: EOB and omphalocele were absent, nevertheless, the ratio of ROCK1–/– mice was sub-Mendelian since 60% died in utero before E9.5." (PMID 35043239, 2022). "To answer whether ROCK1KD/KD mice reproduce the developmental phenotypes reported in ROCK1–/– mice such as EOB and omphalocele, we analyzed the genotype distribution at birth." (PMID 35043239, 2022).
osteoarthritis (5 papers, 2020 to 2025). A noninflammatory degenerative joint disease occurring chiefly in older persons, characterized by degeneration of the articular cartilage, hypertrophy of bone at the margins and changes in the synovial membrane. "Furthermore, the exosomes derived from curcumin-treated MSCs modulate the expression of ROCK1 and NF-kB which are increased in osteoarthritis." (PMID 40851668, 2025). "Besides, the therapeutic effects of curcumin in osteoarthritis are possibly exerted via modulating the miR-143/ROCK1/TLR9 and miR-124/NF-kB pathways." (PMID 36177350, 2022).
papillary thyroid carcinoma (5 papers, 2019 to 2023). "The lncRNA DLEUI increases the expression of rho associated coiled-coil containing protein kinase 1 (ROCK1) via Hsa-miR-421, thereby promoting the progress of papillary thyroid carcinoma." (PMID 35174066, 2021). "DLEU1 can also promote papillary thyroid carcinoma progression by sponging miR-421 and thus increasing ROCK1 expression." (PMID 35619131, 2022).
renal fibrosis (5 papers, 2019 to 2024). A final common manifestation of a wide variety of chronic kidney diseases characterized by glomerulosclerosis and tubulointerstitial fibrosis. "Knockdown of ROCK1 inhibits renal fibrosis and mitochondrial dysfunction, suggesting ROCK1 not only served as an injurious role in mitochondrial homeostasis but also a pro-fibrotic factor in CKD." (PMID 39229866, 2024). "In order to further verify the role of ROCK1 in renal fibrosis, we further evaluated the effects of ROCK1 in vivo." (PMID 39229866, 2024). "To assess the impact of ROCK1 on renal fibrosis, we investigated the effects of ROCK1 knockdown in BUMPT cells subjected to TGF-β treatment." (PMID 39229866, 2024). "In our present study, knockdown of ROCK1 both in vivo and in vitro inhibit renal fibrosis and mitochondrial dysfunction, suggesting ROCK1 not only served as an injurious role in mitochondrial homeostasis but also a pro-fibrotic factor in CKD." (PMID 39229866, 2024). "Then, we found miR-182 suppressed the expression of ROCK1 in both in vitro and in vivo models of renal fibrosis." (PMID 39229866, 2024). "Rock1−/− mice showed attenuated progression of renal fibrosis during streptozotocin-induced diabetic injury, whereas in the unilateral ureteral obstruction model, Rock1−/− mice developed unaffected fibrosis in the kidney." (PMID 32178482, 2020). "Collectively, these findings suggest that miR-182 might directly target ROCK1 mRNA to suppress its expression in renal fibrosis." (PMID 39229866, 2024). "Taking together, these results indicate that blocking ROCK1 may attenuated renal fibrosis through inhibiting mitochondrial dysfunction." (PMID 39229866, 2024). "Interestingly, in renal fibrosis, RhoA/ROCK1 aggravates renal fibrosis by activating the NOX4/ROS signalling pathway." (PMID 32496208, 2020). "Importantly, our results also showed that ROCK1 knockdown could inhibit the expression of Drp1, indicating blocking ROCK1 could attenuated mitochondrial division during renal fibrosis." (PMID 39229866, 2024). "Thus, our findings suggest that circPWWP2A may promote renal interstitial fibrosis by modulating miR-182/ROCK1-mediated mitochondrial dysfunction, which may provide a potential therapeutic target for renal fibrosis." (PMID 39229866, 2024). "ROCK1 could promote mitochondrial dysfunction, finally aggravating renal fibrosis." (PMID 39229866, 2024). "In the study of renal disease, it was found that RhoA/ROCK1 is the upstream signal molecule of NOX4/ROS, and the activation of the RhoA/ROCK1 signal pathway can upregulate the expression of NOX4/ROS, promote the differentiation of renal myofibroblasts, and aggravate renal fibrosis." (PMID 34135982, 2021).
COVID-19 (4 papers, 2021 to 2025). A disease caused by infection with severe acute respiratory syndrome coronavirus 2. "Inhibitors of RHO-Kinase 1 (ROCK1) have been proposed to have beneficial effects against the severe acute respiratory distress syndrome (ARDS) associated with COVID-19 as ROCK1 contributes to a burst in inflammation leading to ARS." (PMID 35085325, 2022). "Our study also identified numerous new kinases, such as DNA-PK, PKG1, ROCK1/, PKCδ, and GRK2, providing additional actional targets for the development of immunomodulatory therapies for COVID-19." (PMID 38389037, 2024). "The hypermethylated genes with the lowest p values for hospitalized COVID-19 patients at inclusion (T1) vs. at 6 weeks post-inclusion (T2) were PARP9, ABCA1, MX1, OAS1, ARID5B, and the hypomethylated genes included TMEM131, ROCK1, IFNGR1, CFAP61, VRK2, and C6orf138." (PMID 41227320, 2025).
lymphoma (4 papers, 2021 to 2024). A malignant (clonal) proliferation of B- lymphocytes or T- lymphocytes which involves the lymph nodes, bone marrow and/or extranodal sites. "Primary lymphoma cell lines were established from mice expressing a single Eμ-Myc allele, and either two alleles of WT Rock1 (Eμ-Myc; Rock1 WT) or two alleles of caspase-resistant Rock1 with the D1113A mutation (Eμ-Myc; Rock1 NC)." (PMID 38616733, 2024). "In malignant lymphomas, mutations can influence the correct assembly of the cytoskeleton and thus the ability to migrate (e.g., ROCK1 mutation in Hodgkin lymphoma, RHOA mutations in AITL and DLBCL, and ACTB mutations in DLBCL)." (PMID 34680356, 2021). "Eμ-Myc; Rock1 WT mice succumbed to lymphoma with a median survival of 98 days and a maximum survival of 324 days, whereas Eμ-Myc; Rock1 NC mice had a 45% longer median survival of 142 days and a maximum survival of 538 days." (PMID 38616733, 2024). "Therefore, additional mutations acquired during transformation likely made the lymphoma cells independent of microenvironmental responses associated with expression of the caspase-resistant ROCK1 NC protein in the transplanted bone marrows." (PMID 38616733, 2024). "In addition, the absence of survival advantage in mice transplanted with transformed Eμ-Myc; Rock1 NC lymphoma cells suggests that they had become insensitive to growth inhibitory stimuli that they might be exposed to in the Eμ-Myc; Rock1 WT host bone marrows." (PMID 38616733, 2024).
nonalcoholic fatty liver disease (4 papers, 2020 to 2022). "Cumulatively, circ_0057558/miR-206/ROCK1/AMPK was found to be a functional axis in the etiology of nonalcoholic fatty liver disease." (PMID 36177350, 2022). "As reported, NEAT1 accelerates the accumulation of hepatic lipid in nonalcoholic fatty liver disease via binding to miR-146a-5p to increase ROCK1 expression." (PMID 31868202, 2020). "In liver tissue, ROCK1/AMPK/sterol regulatory element-binding protein-1c (SREBP1c) axis was reported to regulate hepatic lipogenesis and contribute to nonalcoholic fatty liver diseases." (PMID 35769086, 2022). "In addition, ROCK1/AMPK/SREBP1c axis was reported to regulate hepatic lipogenesis and contribute to nonalcoholic fatty liver diseases." (PMID 35769086, 2022).